ACSL4 (acyl-CoA synthetase long chain family member 4)
Diseases named in the same sentence as ACSL4 in open-access papers (continued):
Sharing a sentence is not in itself a finding about the gene and the disease.
acne (1 paper, 2025). An inflammatory process of the sebaceous glands which is characterized by comedones, nodules, papules and/or pustules on the skin. "Thus, the downregulation of ACSL4 may reduce sebaceous gland synthesis, inhibit ferroptosis-related cell damage, decrease arachidonic acid activation, and synthesis of pro-inflammatory cytokines, suggesting a potential therapeutic mechanism for isotretinoin in the treatment of severe acne." (PMID 40860874, 2025).
adrenocortical cancer (1 paper, 2020). "We further analyzed the expression levels of ACSL4 and GPX4 in three adrenocortical cancer cell lines NCI-H295R30, CU-ACC1 and CU-ACC231 which were subsequently used for all further experiments." (PMID 32184394, 2020).
adrenocortical tumor (1 paper, 2020). "In addition, studies with Murine Y1 adrenocortical tumor cells have shown that the intracellular level of ARA in mitochondria is controlled by acyl-CoA synthetase long chain family member 4 (ACSL4) and acyl-CoA thioesterase 2 (ACOT2)." (PMID 32469895, 2020).
alcoholic hepatitis (1 paper, 2023). Acute hepatitis resulting from ingestion of alcohol. "Furthermore, miR-214, which is upregulated in alcoholic hepatitis, increases ferroptosis by activating ferroptosis-driver genes (ACSL4, PRKAA2, and SLC38A1) through AGO2-dependent transcriptional mechanisms." (PMID 37626043, 2023).
allergic disease (1 paper, 2024). An immune response that occurs following re-exposure to an innocuous antigen, and that requires the presence of existing antibodies against that antigen. "Collectively, ACSL4-dependent ferroptosis in alveolar epithelial type II cells facilitates Bet v 1-induced TH2/TH17-related inflammatory and epithelial damage, orchestrating allergic disease and being capable of acting as an intervention target for allergy therapy." (PMID 38395974, 2024).
Alport syndrome (1 paper, 2016). A rare renal disease characterized by glomerular nephropathy with hematuria progressing to end-stage renal disease (ESRD), frequently associated with sensorineural deafness, and occasionally with ocular anomalies. "The deficiency of ACSL4 is correlated with the mental retardation and Alport syndrome." (PMID 27171439, 2016).
autoimmune hepatitis (1 paper, 2021). Hepatitis caused by autoantibodies. "The dysregulation of COX2, ACSL4, GPX4, and FTH1 expression, as well as MDA and iron overload levels, suggest an important role for ferroptosis in S100-induced autoimmune hepatitis." (PMID 34966478, 2021). "In addition, the expression of ferroptosis biomarkers (including COX2, ACSL4, and FTH1) was significantly increased in mice with S100-induced autoimmune hepatitis after specific knockdown of GPX4." (PMID 34966478, 2021).
Barrett’s oesophagus (1 paper, 2025). "ACSL4 inhibition improves oesophageal tissue damage that is caused by chronic acid reflux which drives the progression of Barrett’s oesophagus to oesophageal adenocarcinoma." (PMID 40381373, 2025).
carcinomas of the colon (1 paper, 2013). "Elevated levels of ACSL4, a member of the long-chain ACS family, has been reported in carcinomas of the colon and liver, and in hormone receptor-negative cancers of the prostate and breast." (PMID 23936004, 2013).
cerebrovascular disease (1 paper, 2025). "ACSL4 thus represents a risk factor in cerebrovascular disease." (PMID 41288931, 2025). "While numerous studies have investigated targeting ACSL4 to mitigate brain injury in cerebrovascular disease, the roles of ACSL1 and ACSL3 as key regulators of ferroptosis remain underexplored." (PMID 41288931, 2025). "Additionally, it remains to be determined whether ACSL4, as a central enzyme in fatty acid metabolism, influences glycolipid metabolism in patients with cerebrovascular disease." (PMID 41288931, 2025). "The ACSL family consists of five isoforms—ACSL1, ACSL3, ACSL4, ACSL5, and ACSL6—each of which has been implicated in the pathogenesis, treatment, and prognosis of diverse conditions, including metabolic disorders, cancers, cardiovascular and cerebrovascular diseases, and other clinical conditions." (PMID 41288931, 2025). "Among cerebrovascular diseases, the ACSL family—particularly ACSL4—has been extensively studied." (PMID 41288931, 2025).
cervical adenocarcinoma (1 paper, 2022). An adenocarcinoma arising from the cervical epithelium. "By analyzing the GEPIA database, it was found that ACSL4 level was down-regulated in cervical squamous cell carcinoma and cervical adenocarcinoma compared with normal tissues." (PMID 35321435, 2022).
clear cell renal cell carcinoma (1 paper, 2026). "A study using Oncomine and The Cancer Genome Atlas (TCGA) databases together with in vitro clear cell renal cell carcinoma showed that suppression of ACSL4 increased ferroptosis resistance, whereas overexpression of ACSL4 could restore ferroptosis sensitization in cancer cells." (PMID 41541703, 2026).
deafness (1 paper, 2022). An inherited or acquired condition characterized by the complete loss of the ability to hear from one or both ears. "Several previous studies have reported clinical cases of ACSL4 gene deletion with deafness." (PMID 35355868, 2022).
dementia (1 paper, 2020). Loss of intellectual abilities interfering with an individual's social and occupational functions. "ACSL4, ECHS1, and HSP90B1 have no reported association with AD or related dementias, however, which suggests that our study has the potential to identify new targets in the molecular pathogenesis of this disease." (PMID 33116184, 2020).
disc degeneration (1 paper, 2025). "Overall, these findings establish the crucial protective role of CMA in preventing IVDD through the degradation of ACSL4, providing novel insights for developing therapeutic strategies targeting CMA activation to alleviate disc degeneration and associated chronic pain." (PMID 41270209, 2025).
enterovirus infection (1 paper, 2022). "The sustained expression level of ACSL4 indicates that it plays an essential role in virus production, since most of the host translation is shut off upon enterovirus infection." (PMID 35038927, 2022).
epileptic seizures (1 paper, 2020). "Other identified ferroptosis targets including SLC7A11 (ANOVA, F = 10.68, p < 0.001), 5-LOX (ANOVA, F = 23.53, p < 0.001) and ACSL4 (ANOVA, F = 4.521, p = 0.008) were slightly or hardly affected in KA-induced epileptic seizures when treatment with lapatinib." (PMID 33362556, 2020).
esophageal cancer (1 paper, 2025). A primary or metastatic malignant neoplasm involving the esophagus. "Suconazole increases the expression of ACSL4, significantly increasing lipid peroxide levels, which can increase radiosensitivity of esophageal cancer cells." (PMID 40709182, 2025).
fibrosis (1 paper, 2025). the formation of excess fibrous connective tissue in an organ or tissue in a reparative or reactive process. "In this study, we show that the expression of ACSL4 was elevated in lung tissues from bleomycin (BLM)-induced fibrosis models and positively correlated with α-smooth muscle actin (αSMA)." (PMID 40867551, 2025).
gastrointestinal stromal tumor (1 paper, 2024). "As a kind of enzyme involved in the synthesis of PE, the level of ACSL4 is reduced in imatinib-resistant gastrointestinal stromal tumors cells, while upregulating the expression ACSL4 can induce ferroptosis and alleviate the resistance of imatinib." (PMID 38711989, 2024).
gestational diabetes mellitus (1 paper, 2025). "Ferroptosis and gestational diabetes mellitus (GDM) converge at multiple molecular intersections, notably through the involvement of key regulatory genes including GPX4, SLC7A11, ACSL4, and LPCAT3." (PMID 41020807, 2025).
glomerular disease (1 paper, 2025). "Our snRNA-seq approach enabled identification of disease-specific podocyte subpopulations, revealing that the ELOVL7 → LC-PUFA → ACSL4 axis constitutes a previously unrecognized pathway driving podocyte vulnerability to lipid peroxidation and glomerular disease progression." (PMID 41285716, 2025).
gout (1 paper, 2024). A condition characterized by painful swelling of the joints, which is caused by deposition of urate crystals. "In conclusion, our study analyzed the expression changes of ferroptosis-related proteins ACSL4, VDAC2, GPX4, and GSS in the urinary exosomes of gout patients." (PMID 39606034, 2024). "ROC curve analysis revealed that the presence of ACSL4, VDAC2, and GPX4 in urinary exosomes possesses substantial predictive value for acute gout attacks." (PMID 39606034, 2024). "Specifically, changes in ferroptosis-related proteins such as ACSL4, VDAC2, GPX4, and GSS may serve as promising biomarkers for the monitoring of acute gout attacks." (PMID 39606034, 2024). "Moreover, ROC analysis in our study indicated that ACSL4, VDAC2, and GPX4 have strong predictive abilities for acute gout attacks, with AUC values of 0.771, 0.833, and 0.722, respectively." (PMID 39606034, 2024).
head and neck squamous cell carcinoma (1 paper, 2025). A squamous cell carcinoma that arises from any of the following anatomic sites: lip and oral cavity, nasal cavity, paranasal sinuses, pharynx, larynx, and salivary glands. "For instance, SUMO1 can promote the SUMOylation of ACSL4, stabilising its expression and leading lipid peroxide accumulation, and inducing ferroptosis in squamous carcinoma cells, which drives head and neck squamous cell carcinoma progression." (PMID 40374601, 2025).
hematoma (1 paper, 2025). A hematoma is a collection of blood from a vascular structure into an extravascular space. "Additionally, the levels of GPX4 and SLC7A11 in the brain tissue around the hematoma were significantly reduced, while the levels of ACSL4 and COX-2 were significantly increased (P < 0.001)." (PMID 39601768, 2025).
hyperhomocysteinemia (1 paper, 2025). A serious metabolic condition caused by mutations in the MTHFR gene, medications, or nutritional deficiency. "Hyperhomocysteinemia decreased the expression level of SLC7A11 while concurrently upregulating ACSL4 expression." (PMID 40768425, 2025). "In contrast, β-catenin overexpression antagonized the effects of hyperhomocysteinemia by upregulating SLC7A11 expression and downregulating ACSL4 expression." (PMID 40768425, 2025).
IgA nephropathy (1 paper, 2025). "Mechanistically, the downregulation of peroxisome proliferator-activated receptor α mediates the regulation of fatty acid-binding protein 1 on GPX4 and ACSL4, leading to ferroptosis and promoting the development of IgA nephropathy." (PMID 41425591, 2025).
imbalance (1 paper, 2025). "Research indicates that ACSL4, as a key lipoxygenase, shows a positive correlation between its expression and the severity of lipid metabolic imbalance." (PMID 41422632, 2025).
keratoconus (1 paper, 2025). A degenerative, structural disorder of the eye, characterized by a cone-shaped protrusion of the cornea. "ACSL4 is the most promising biomarker for keratoconus and is expressed predominantly in corneal stromal cells." (PMID 41394869, 2025).
lung diseases (1 paper, 2023). "Statistical analyses demonstrated that mRNA expression of ACSL1, ACSL3 and ACSL4 in lung and airway epithelial cells among lung diseases." (PMID 36639836, 2023).
malaria (1 paper, 2020). Malaria is a serious and sometimes fatal disease caused by a parasite that commonly infects a certain type of mosquito which feeds on humans. "The high concentration of the AA related lipid mediators found in malaria infected mice may act downregulating the Acsl4, promoting the inflammatory response." (PMID 32664933, 2020).
Myocardial fibrosis (1 paper, 2023). "Consistent with the mRNA level, the expression of α-SMA, GPX4, and ACSL4 proteins indicated that inhibition of ferroptosis alleviated myocardial fibrosis induced by Ang II and PE in cardiomyocytes." (PMID 37288112, 2023).
nephrotoxicity (1 paper, 2025). Toxicity that causes injury to the kidney or damages its function. "The expression of TFRC, ACSL4, and STEAP3, all of which promote ferroptosis, was significantly upregulated in the APAP-induced nephrotoxicity group." (PMID 41249093, 2025).
nonalcoholic fatty liver (1 paper, 2014). "Similar evidence (over-expression at 6 h, 24 h, and 21d) was observed for acyl-CoA synthetase long-chain family member 4 (ACSL4), a gene that was reported to be over-expressed in nonalcoholic fatty liver (NAFL)." (PMID 25194679, 2014).
osteoporosis (1 paper, 2025). A condition of reduced bone mass, with decreased cortical thickness and a decrease in the number and size of the trabeculae of cancellous bone (but normal chemical composition), resulting in increased fracture incidence. "And the key proteins discovered from animal models, such as GPX4, SLC7A11, ACSL4, etc., are extremely difficult and unethical to obtain from healthy human bodies, especially in early bone tissue samples of osteoporosis." (PMID 41551515, 2025).
pemphigus (1 paper, 2025). Pemphigus is a group of rare autoimmune diseases that cause blistering of the skin and mucous membranes (mouth, nose, throat, eyes, and genitals).This conditioncan occur at any age, but often strikes people in middle or older age. "We also developed a nomogram model integrating the expression scores of ACSL4, SAT2, and XBP1 to predict pemphigus risk, which showed good calibration and significant clinical utility." (PMID 40612574, 2025). "Results revealed that SAT2 and XBP1 were up-regulated in the pemphigus group compared to the control group, whereas ACSL4 expression was reduced in the pemphigus group." (PMID 40612574, 2025). "Collectively, these findings indicate that ACSL4, SAT2, and XBP1 exhibit consistent and significant diagnostic value, supporting their candidacy as promising diagnostic biomarkers for pemphigus." (PMID 40612574, 2025). "To enhance clinical decision-making, we developed a nomogram model that integrates the expression scores of ACSL4, SAT2, and XBP1 for predicting the risk of pemphigus." (PMID 40612574, 2025). "Differential expression analysis was conducted to investigate the expression patterns of the five genes (XBP1, FBXO45, SAT2, AIFM1, and ACSL4) and eight other DEGs associated with ferroptosis (G3BP1, WBP11, TET2, IRF8, FASN, GDPD5, H1-4, and HUWE1) in both the pemphigus and control groups." (PMID 40612574, 2025).
peripheral nerve injury (1 paper, 2022). Injury to a peripheral nerve. "Neuropathic pain (NP) induced by peripheral nerve injury has been shown to be associated with the over-expression of ACSL4 and ferroptosis." (PMID 36507355, 2022). "Although some recent studies have proposed the key roles of ACSL4 in the mechanism of neuropathic pain induced by peripheral nerve injury, few studies are involved in the regulation effect of ACSLs in the SCs." (PMID 36507355, 2022).
polycystic ovary syndrome (1 paper, 2022). A disorder that manifests as multiple cysts on the ovaries. "The suppressive action of TfR/NADPH oxidase 1/PTEN, which induced kinase 1 acyl-CoA synthetase long chain family member 4 signaling on folliculogenesis, is a likely target for polycystic ovary syndrome." (PMID 36293552, 2022).
preeclampsia (1 paper, 2024). Preeclampsia is a hypertensive disorder of pregnancy that is characterized by new-onset hypertension with proteinuria presenting after 20 weeks of gestation, and depending on mild or severe forms may initially present with severe headache, visual disturbances, and hyperreflexia. "An increased expression of ACSL-4 and ALOX-5 together with decreased GPX4 levels in the placenta has been associated with trophoblastic ferroptosis and different obstetric complications such as preeclampsia." (PMID 38790696, 2024).
Premature ovarian insufficiency (1 paper, 2025). Amenorrhea due to loss of ovarian function before the age of 40. "In chemotherapy-induced primary ovarian insufficiency, the transcriptional increase in ACSL4 and the iron release mediated by HO-1 are significant." (PMID 41226419, 2025).
Psoriasiform dermatitis (1 paper, 2025). A skin abnormality characterized by redness and irritation, with thick, red skin that displays flaky, silver-white patches (scales). "Compared with normal lesions, lipid ROS and ferrous iron, the expression of acyl-CoA synthetase long-chain family member 4 (ACSL4) were increased, and the expression of GPX4 was decreased in psoriatic lesions, Fer-1 significantly suppresses ferroptosis and alleviates psoriasiform dermatitis." (PMID 40245702, 2025).
psychosis (1 paper, 2023). "Our results demonstrate an increased presence of iron deposits that are accompanied by a further expression of TFRC, ACSL-4, ALOX-5, MDA, and GPX4—all of which are observed in the placenta tissue of women who have suffered from a first episode of psychosis." (PMID 36671505, 2023).
sarcopenia (1 paper, 2025). Progressive decline in muscle mass due to aging which results in decreased functional capacity of muscles. "Our analysis revealed significant differences in the mRNA and protein levels of GPX4 and ACSL4 in sarcopenia patients compared to controls." (PMID 40309008, 2025).
septic shock (1 paper, 2025). Shock caused by infection; frequently caused by gram negative bacteria, although some cases have been caused by other bacteria, viruses, fungi, and protozoa; characterized by fever, chills, tachycardia, tachypnea, and hypotension. "ACSL4 levels were positively correlated with SOFA (Rho = 0.354, p-value < 0.0001), APACHE II (Rho = 0.317, p-value < 0.0001), and septic shock (Rho = 0.274, p-value = 0.003) scores but negatively correlated with the GCS score (Rho = -0.218, p-value = 0.018)." (PMID 40264754, 2025). "Among patients with septic shock versus those without, baseline serum levels of ACSL4, PTGS2, and LA were significantly higher in those with septic shock." (PMID 40264754, 2025).
Telangiectasia (1 paper, 2023). Telangiectasias refer to small dilated blood vessels located near the surface of the skin or mucous membranes, measuring between 0.5 and 1 millimeter in diameter. "We also noted that RT can not only restrict GSH synthesis by activating the ataxia-telangiectasia mutated gene to inhibit SLC7A11 of glutamate-cystine antiporter Xc- but also induce ferroptosis by inducing the expression of ROS and ACSL4." (PMID 37007068, 2023).
thrombotic microangiopathy (1 paper, 2017). The syndromes of microangiopathic hemolytic anemia, thrombocytopenia, and variable signs of organ impairment, due to platelet aggregation in the microcirculation. "We detected robust immunostaining of ACSL4 in human ATI seven days post-transplantation, as well as in severe thrombotic microangiopathy of native kidney." (PMID 28551825, 2017).
thymoma (1 paper, 2022). A neoplasm arising from the epithelial cells of the thymus. "Among the 33 cancer types, ACSL4 expression was most correlated with TMB in ACC, whereas FANCD2, HIF3A, HSPA5, and PSMB7 were most correlated with TMB in thymoma (THYM)." (PMID 35652069, 2022).
toxoplasmosis (1 paper, 2025). A parasitic disease contracted by the ingestion or fetal transmission of toxoplasma gondii. "In this study, we found that T. gondii-induced tissue pathology is associated with reduced GPX4 expression and high expression of ACSL4, suggesting a key role of GPX4 and ACSL4 in mediating the pathogenesis of toxoplasmosis." (PMID 40667873, 2025).